SIRT6 (sirtuin 6)
Diseases named in the same sentence as SIRT6 in open-access papers (continued):
Sharing a sentence is not in itself a finding about the gene and the disease.
pancreatic cancer (continued). "Consistent with this hypothesis, a previous study suggested that elevated SIRT6 promotes pancreatic cancer cell migration and invasion and may play a vital role in disease progression." (PMID 27777384, 2016). "More importantly, in pancreatic cancer, SIRT6 could promote the expression of inflammatory factor IL-8, which could promote local inflammation and further promote angiogenesis, playing a key role in the occurrence and metastasis of pancreatic cancer." (PMID 37888452, 2023). "Previous reports have demonstrated that SIRT6 could promote the expression of inflammatory factor IL-8, which could promote local inflammation and further promote angiogenesis, playing a key role in the occurrence and metastasis of pancreatic cancer." (PMID 37888452, 2023). "Little is known of the other sirtuins, with the exception of SIRT 6, which has been reported to promote cytokine production and migration in pancreatic cancer cells, accordingly it was suggested that SIRT6 inhibitors may serve as a novel treatment for pancreatic cancer." (PMID 26121130, 2015). "For instance, SIRT1 and SIRT7 were reported to promote pancreatic cancer progression, while SIRT2, SIRT4, SIRT5, and SIRT6 seem to play a tumor suppressor role." (PMID 41391757, 2025). "Treatment of pancreatic cancer cell lines with Compound 8a increased acetylation of histone H3K9, consistent with cellular activity against Sirt6." (PMID 38474697, 2024). "In contrast to typical sirtuin inhibition modes, the recommended Sirt6 inhibitor, JYQ-42, allosterically decreases Sirt6 deacetylase activity and demonstrates translational promise in pancreatic cancer cell models." (PMID 38474697, 2024). "Consequently, SIRT6’s multifaceted role in promoting the synthesis of Ca2+ mobilizing second messengers and regulating Ca2+-dependent transcription factors underscores its potential use as a therapeutic target to mitigate cancer-induced inflammation, angiogenesis and metastasis in pancreatic cancer." (PMID 39682281, 2024). "In the context of PDAC, SIRT6 elevates the expression of pro-inflammatory cytokines and chemokines, such as IL-8 and TNF, thereby fostering an inflammatory phenotype in pancreatic cancer cells." (PMID 39682281, 2024). "JYQ-42 increased acetylation of the Sirt6 substrates histone H3K9, H3K18, and H3K56 in pancreatic cancer cell lines in a concentration-dependent manner, consistent with on-target Sirt6 inhibition." (PMID 38474697, 2024). "A link between SIRT6 and Ca2+ homeostasis, involving TRPM2 channels, had been previously demonstrated in pancreatic cancer cells, but a correlation between SIRT6 and the ATP/P2X/Ca2+ pathway has not been highlighted yet." (PMID 37047732, 2023). "Thus, 8a, an inhibitor of SIRT6, may inhibit angiogenesis in pancreatic cancer." (PMID 37888452, 2023). "The pancreas carcinoma cell lines Pa-Tu-8902, YAPC, and DanG had the weakest expression of Sirt6, with values below 0.54." (PMID 35008351, 2021). "Here, we reported the discovery of a pyrrole-pyridinimidazole derivative, 8a, as a new non-competitive SIRT6 inhibitor, and studied its roles and mechanisms in the antitumor activity and sensitization of pancreatic cancer to gemcitabine." (PMID 37542062, 2023). "JYQ-42, as a selective and non-competitive inhibitor of SIRT6, can inhibit cell migration and cytokine production in pancreatic cancer cells, showing potent anti-cancer effects." (PMID 35915188, 2022). "Compound 8a exhibited synergistic cytotoxic effects with gemcitabine in a mouse xenograft model of pancreatic cancer without impacting overall pancreatic function, supporting the potential therapeutic efficacy of Sirt6 inhibition in pancreatic cancer identified in previous studies." (PMID 38474697, 2024).
lung cancer (31 papers, 2014 to 2025). A malignant neoplasm involving the lung. "High cytoplasmic SIRT6 expression is strongly implicated in poor prognosis and diminished chemosensitivity in lung cancer patients." (PMID 39940397, 2025). "Moreover, SIRT6 expression is associated with poor prognosis of breast, gastric, colorectal, and lung cancer patients, and higher SIRT6 expression is associated with chemoresistance." (PMID 30524965, 2018). "We first used online databases and found that SIRT6 is upregulated in lung cancer, and the overall survival of lung cancer patients with high SIRT6 expression is shorter, suggesting that SIRT6 is associated with poor prognosis of lung cancer, especially EGFR mutant NSCLC." (PMID 35915188, 2022). "This study demonstrated a novel molecular mechanism underlying the chemopreventive effect of CK in lung cancer cells, involving PARP-1 activation-mediated parthanatos, which is promoted by SIRT6 degradation." (PMID 39940397, 2025). "In contrast, SIRT6 promotes ROS generation in various cancer-cell types, including lung cancer cells, leading to cell death and mitochondrial dysfunction." (PMID 39940397, 2025). "Isoorientin enhances ferroptosis while overcoming drug resistance in lung cancer via the SIRT6/Nrf2/GPX4 signaling axis." (PMID 38515565, 2024). "On the other hand, SIRT6 functions as an oncogene in lung cancer, skin cancer, and multiple myeloma." (PMID 38135684, 2023). "In contrast, there are research reports that emphasize the importance of Sirt6 in regulating the random acetylation of Sirt1 with respect to lung cancer." (PMID 38020163, 2023). "For lung cancer, especially NSCLC, there are reports supporting our research: SIRT6 is highly expressed in NSCLC, and SIRT6 is associated with poor prognosis of NSCLC patients." (PMID 35915188, 2022). "For example, SIRT6 contributes to the invasiveness and metastasis in lung cancer and ovarian cancer." (PMID 34225779, 2021). "While in other cancer types, such as lung cancer and melanoma, SIRT6 was up-regulated and act as a tumor promoter." (PMID 32158696, 2020). "Reduced SIRT6 expression mediates the augmentation of radiation-induced apoptosis via cAMP signaling in lung cancer cells." (PMID 31956359, 2020). "Patients with high cytosol expression but low nuclear expression of SIRT6 can have poor clinical outcomes of lung cancer." (PMID 31956359, 2020). "Although CK induces apoptosis in lung cancer cells, the involvement of SIRT6 in this process remains unclear." (PMID 39940397, 2025). "Therefore, SIRT6 is a potential biomarker for the chemopreventive effect of CK in lung cancer cells, but further studies on SIRT6 are needed for the clinical application of CK." (PMID 39940397, 2025). "Another study demonstrated that MIR186 could inhibit lung cancer progression through targeting SIRT6." (PMID 38183079, 2024). "Among the reports in lung cancer, SIRT6 can regulate EMT and invasion of NSCLC cells." (PMID 35915188, 2022). "In lung cancer, SIRT6 is overexpressed in non-small-cell lung cancer (NSCLC) cell lines." (PMID 35463332, 2022). "Bioinformatics analysis using UALCAN indicated that SIRT6 expression was upregulated in lung cancer tissues compared to normal lung tissues (sample number in LUSC group: normal 52, primary tumor 503, p < 0.001) (sample number in LUAD group: normal 59, primary tumor 515, p < 0.001)." (PMID 35915188, 2022). "In lung cancer models, SIRT-6 overexpression may decrease HIF-1α and VEGF expression and promote prolyl hydroxylase-2 expression, thereby inhibiting angiogenesis and tumor growth." (PMID 35906622, 2022). "Therefore, to understand the impact of SIRT6 on the prognosis of lung cancer patients, we used public databases to obtain survival data of NSCLC patients." (PMID 35915188, 2022). "Reduced SIRT6 expression potentiates γ-ray-induced apoptosis of NSCLC cells, suggesting that SIRT6 may have oncogenic activity in lung cancer." (PMID 31591350, 2019).
lung cancer (continued). "SIRT6 transgenesis extends lifespan in male mice; this effect might occur in part through a reduction in lung cancer incidence in SIRT6 overexpressors." (PMID 25085992, 2014). "Similarly, SIRT6 overexpression in vivo seems to provide some protection against lung cancers in mice." (PMID 25085992, 2014). "Hence, targeting SIRT6 might be a new promising epigenetic therapeutic approach to evade Nrf2/Keap1-powered cellular rescue pathways in lung cancer." (PMID 38235110, 2023). "This work investigated the involvement of SIRT6 and PARP-1 in the anticancer effects of CK in lung cancer." (PMID 39940397, 2025). "We investigated the involvement of silent information regulator 6 (SIRT6) and poly (ADP-ribose) polymerase 1 (PARP-1) in the anticancer effects of CK in lung cancer." (PMID 39940397, 2025). "In the A549 lung cancer cell line, α-hederin was shown to inhibit c-Myc and HIF-1α by increasing the expression of SIRT6 to inhibit glycolysis and further inhibit the proliferation of A549 cells." (PMID 35463332, 2022). "SIRT6 has been reported to inhibit Twist 1 and EMT in lung cancer and idiopathic pulmonary fibrosis, respectively." (PMID 34702956, 2021). "We examined the effects of SIRT6 expression on the ERK1/2/MMP9 pathway, which is involved in lung cancer metastasis and invasion." (PMID 27777384, 2016). "In terms of mechanism, isoorientin acts as a modulator that controls the SIRT6/NRF2/GPX4 signaling pathway (downregulation of the expression of SIRT6 protein, NRF2, and GPX4), thereby regulating ferroptosis and reversing drug resistance in lung cancer cells." (PMID 37760042, 2023). "Previous study showed that SIRT6 might act as antioncogenesis factor by inhibiting HIF-1α, an angiogenesis-promoting molecule, in lung cancer, and by inhibiting c-Myc gene and ribosome biosynthesis." (PMID 35136826, 2022). "Whole-body SIRT6 overexpression extends lifespan in male mice specifically by attenuating insulin–IGF-1-like signaling (IIS), and potentially by decreasing the incidence of lung carcinoma." (PMID 25085992, 2014).
heart failure (30 papers, 2015 to 2025). Inability of the heart to pump blood at an adequate rate to meet tissue metabolic requirements. "After adjustment for established risk factors (age, NIHSS, heart failure, atrial fibrillation, and C reactive protein), SIRT6 levels were negatively associated with mortality." (PMID 36443316, 2022). "Our previous findings suggest that SIRT6 levels decrease in heart failure patients and this downregulation is linked to the development of cardiac hypertrophy and heart failure in mice." (PMID 36109503, 2022). "Our previous study showed that Sirt6 is a cardioprotective molecule, and the loss of Sirt6 leads to heart failure." (PMID 33934090, 2021). "Sirt6 is a negative regulator of the insulin-like growth factor-1-protein kinase B pathway, which is implicated in the development of heart failure." (PMID 29234485, 2017). "Deficiency of Sirt6 in cardiomyocytes results in the accumulation of lactate due to impaired glucose oxidation, leading to various comorbidities relating to the heart, including heart failure." (PMID 33442387, 2020). "In line with this, SIRT6 was downregulated in both animal models of heart failure and patient hearts affected by chronic heart failure." (PMID 39215785, 2025). "Another study found that SIRT6 expression is significantly reduced in the hearts of patients with chronic heart failure and animal models of heart failure." (PMID 39062982, 2024). "Researchers also revealed the cardioprotective effect of Sirt6 in a mouse model of Transverse Aortic Constriction (TAC)-induced heart failure." (PMID 37497437, 2023). "In rodents, genetic overexpression of SIRT6 partially prolongs lifespan by regulating IGF-AKT signaling, contributing to SIRT6 function in preventing cardiac aging and heart failure." (PMID 35855341, 2022). "In a mouse model of transverse aortic constriction (TAC)-induced heart failure, SIRT6 maintained telomere integrity, thereby decreasing cardiac fibrosis and infarct size." (PMID 34650436, 2021). "There is evidence that down-regulation IGF-AKT signaling directly by Sirt6 is capable of blocking heart failure and myocardial disease." (PMID 32745152, 2020). "Heart failure is one of the age-related disorder in mammals, where the IGF-Akt on sustained activation promotes hypertrophy and heart failure, whereas Sirt6 impedes IGF-Akt signaling via c-Jun by deacetylation of H3K9." (PMID 33442387, 2020). "Future studies should focus on exploring the mechanisms by which SIRT6 protects the heart in our in vivo model of TAC-induced heart failure." (PMID 28659816, 2017). "Myocardial samples from patients with heart failure showed markedly reduced SIRT6 levels, indicating an important role of the SIRT6 signaling in heart disease." (PMID 29069788, 2017). "In the present study, we investigated the role of SIRT6 and TERT in cardiovascular disease in a mouse model of transverse aortic constriction (TAC)-induced heart failure and explored the underlying mechanisms." (PMID 28659816, 2017). "In conclusion, we used a mouse model of TAC-induced heart failure to explore the role of SIRT6 and the modulation of telomere length and structure in the protection against cardiovascular dysfunction." (PMID 28659816, 2017). "In the present study, we examined the role of SIRT6 in TAC-induced heart failure and the involvement telomere integrity in the protective effects of SIRT6 on cardiovascular function." (PMID 28659816, 2017). "Second, different sirtuin isoforms, mainly SIRT3 and SIRT6, might be considered as mitochondrial markers of heart failure and require future dedicated studies." (PMID 38255934, 2024). "Hence, SIRT6 is indispensable for producing glycolytic substrates in the mitochondria for cardiac oxidation/utilization, and is, at least partially, critical for heart failure in cardiac-specific Sirt6-KO mice." (PMID 36465178, 2022).
heart failure (continued). "In cardiovascular diseases, Sirt6 is involved in regulating the heart's multiple pathophysiological conditions, including hypertrophy, atherosclerotic vascular disease, coronary artery disease, and heart failure." (PMID 33442387, 2020). "The levels of SIRT6, TERT, and TRF1 were measured in myocardial tissues of mice exposed to TAC or sham surgery to explore the association of sirtuins and telomere function with TAC-induced heart failure." (PMID 28659816, 2017). "Compared to SIRT1, SIRT3, and SIRT6, studies on SIRT2,541 SIRT4, SIRT5,542 and SIRT7 in heart failure are limited." (PMID 36581622, 2022). "In the present study, we investigated the role of SIRT6 and telomerase in a mouse model of transverse aortic constriction (TAC)-induced heart failure." (PMID 28659816, 2017). "SIRT6 suppresses IGF-Akt signaling, which promotes heart failure when activated." (PMID 34650436, 2021).
endothelial dysfunction (27 papers, 2012 to 2025). In vascular diseases, endothelial dysfunction is a systemic pathological state of the endothelium (the inner lining of blood vessels) and can be broadly defined as an imbalance between vasodilating and vasoconstricting substances produced by (or acting on) the endothelium. "In summary, these results suggested that Ero1α knockdown effectively rescued endothelial dysfunction and inhibited endothelial apoptosis and inflammation in SIRT6 deficiency under OGD/R conditions." (PMID 37598403, 2023). "In the experiment of SIRT6 gene knockout hypertensive mice, it was found that the loss of endothel-specific SIRT6 significantly increased blood pressure, aggravated endothelial dysfunction and cardiac renal injury." (PMID 35752619, 2022). "Previous documents proven that Sirt1-dependent mechanism was wide agreement in DM-associated endothelial dysfunction, therefore we added Sirt6 mRNA- containing EMPs into Sirt1 deficient HUVECs." (PMID 29371988, 2017). "SIRT6 is an important member of sirtuin family that represses inflammation, aging and DNA damage, three of which are causing factors for endothelial dysfunction." (PMID 27249230, 2016). "In addition, miR-122 causes angiotensin II-induced endothelial dysfunction and vascular fibrosis by targeting sirtuin 6 (SIRT6), a negative regulator of the renin-angiotensin system." (PMID 40565979, 2025). "Additionally, SIRT6 deficiency exacerbated endothelial dysfunction, as indicated by reduced protein levels of VE‐cadherin, p‐eNOS and eNOS in SIRT6‐knockdown HUVECs under OGD/R conditions." (PMID 37598403, 2023). "Collectively, SIRT6 activation and/or histone acetyltransferase inhibition may be useful therapeutic approaches to reduce endothelial dysfunction and combat age-associated cardiovascular disease." (PMID 34744793, 2021). "SIRT6 deficiency leads to endothelial dysfunction, growth arrest, and premature senescence." (PMID 33171439, 2020). "Our data, together with a previous observation that lipopolysaccharide-induced reduction of Sirt6 expression is linked to lipopolysaccharide-induced endothelial cell inflammatory reactions, highlight the importance of Sirt6 in preventing endothelial dysfunction caused by cellular stress mechanisms." (PMID 25162034, 2014). "Thus, it may be possible that Sirt6 deficiency in DM patient-derived EMPs induces endothelial dysfunction via the eNOS pathway." (PMID 29371988, 2017). "Thus, activation of SIRT6 may be beneficial for many inflammatory diseases associated with endothelial dysfunction." (PMID 23132960, 2012). "SIRT6 regulates ACE2 by blocking the accumulation of nucleus p-ATF2 in CC-induced endothelial dysfunction." (PMID 41567643, 2025). "It is held that Sirt6 corrects endothelial dysfunction and prevents hypertension and its subsequent complications." (PMID 37497437, 2023). "In supporting of this, Sirt6 overexpression alleviates minute cholesterol crystal-induced endothelial dysfunction." (PMID 37497437, 2023). "Collectively, SIRT6 guards against endothelial dysfunction and senescence by deacetylating H3K9ac to prevent DNA damage and the senescence-associated secretory phenotype." (PMID 35855341, 2022). "All of the phenotypes that we observed in SIRT6 siRNA-treated HUVECs are equivalent to senescent phenotypes (e.g. reduced capacity of new vessel formation, endothelial dysfunction, and high inflammatory responses)." (PMID 33171439, 2020). "Moreover, it has been shown that Sirtuin 6 (SIRT6) has an important role in preventing endothelial dysfunction, a key player in AH and its complications." (PMID 37298378, 2023). "Thus, determination of Sirt6 as a therapeutic target for attenuating endothelial dysfunction has received major clinical interests." (PMID 37497437, 2023).